NCAM1 (neural cell adhesion molecule 1)
Diseases named in the same sentence as NCAM1 in open-access papers (continued):
Sharing a sentence is not in itself a finding about the gene and the disease.
cancer (324 papers, 2006 to 2026). A tumor composed of atypical neoplastic, often pleomorphic cells that invade other tissues. "Of note, Ncam1 encodes the well-known adhesion protein NCAM1 (neural cell adhesion molecule 1), a crucial key player in not only neuronal but also cancer cell migration." (PMID 37880732, 2023). "The loss of E-cadherin during the epithelial-mesenchymal transition in cancer is associated with a positive regulation of NCAM1 and CDH2." (PMID 31921388, 2019). "Hence, an Eph/ephrin-dependent modulation of the DNA methylome of cell adhesion-related genes, as we observed for Ncam1, may be a feasible mechanism of transcriptional regulation underlying reduced cellular motility in cancer cells." (PMID 37880732, 2023). "SCs guide cancer migration via neural cell adhesion molecule 1-dependent protrusion formation, enabling cancer dispersion along nerves." (PMID 40421086, 2025). "Pediatric cancer cells often express NCAM1 (CD56) which is the standard marker used to identify NK cells in the blood." (PMID 39310750, 2024). "NCAM1 has previously been identified as being a marker for cancer-propagating WT cells, suggesting its potential as a marker of transformation from NRs." (PMID 25763109, 2015). "In various cancer types, NK cells are typically categorized into two main subsets, including CD56bright CD16low and CD56dim CD16high, which are characterized by their distinctive expression patterns of the canonical cell markers NCAM1 and FCGR3A." (PMID 39033089, 2024). "Interestingly, the reduction of neural cell adhesion molecule 1 (NCAM1), a member of immunoglobulin superfamily cell adhesion molecules taking part in axon guidance and synapse formation, on SCs results in decreased cancer cell invasion." (PMID 39906323, 2024). "The gene coding for NCAM1, a neuronal cell adhesion molecule with key features for motility regulation in neurons as well as in cancer cells, was significantly increased in expression and its promoter region showed a significant reduction in CpG methylation after ephrinA5 stimulation." (PMID 37880732, 2023). "The Schwann cell-directed regulation of cancer cells may be mediated by neural cell adhesion molecule 1 (NCAM1) in perineural invasion." (PMID 35109895, 2022). "Bioinformatics analyses showed that the expression levels of six out of 25 genes (ERO1B, DPY19L1, NCAM1, RET, MARCH1, and SLC7A8) were associated with LUAD patient survival (p < 0.05), and pathway analyses indicated that major cancer signaling was altered in the subtypes." (PMID 32235589, 2020). "MAX (a MYC interacting partner), miR-150, miR-133a, FOLR1, E2F NCAM1, GAS2L3 and ATF5 are the most significantly associated upstream regulators, while cancer, neurogenesis, metastasis and cellular development are the most important biological functions affected in this subgroup." (PMID 32591022, 2020). "Further, recent studies suggest that upregulation of NCAM1 in Schwann cells could promote cancer cells’ migration and dispersion, suggesting a role for NCAM1 in directing the migration of neoplastic cells towards nerves." (PMID 31248001, 2019). "NCAM1 is also deregulated in other types of cancer, which suggests it might serve as a prognostic biomarker and therapeutic target for FPA." (PMID 31655798, 2019). "Our data reveal the existence of an intricate relationship that sees ZIP6 control the expression, post-translational modification and interactions of NCAM1 in the context of larger morphogenetic rearrangements executed at various stages during development and in cancers." (PMID 28098160, 2017). "In some mammalian cancer paradigms, unpolysialylated NCAM1 might be sufficient and indispensable for a lipid-raft centered signaling program that coordinates the concomitant disassembly of E-cadherin-based adherence junctions and formation of focal adhesions as a prelude to cellular movement." (PMID 27879349, 2016).
cancer (continued). "Expression validation in the transcriptome, TCGA–BLCA, and GSE13507 datasets confirmed the up-regulation of APOL1, DHX34, and TNK2, and the down-regulation of AHNAK, CSPG4, NCAM1, and PCDHB4 in the cancer group." (PMID 40908816, 2025). "In addition, the downregulation of Ncam1 (neural cell adhesion molecule 1) suggests that the eKET diet may impair cell–cell adhesion and communication, potentially disrupting the metastatic cascade, and perhaps enhancing cancer cell killing by Natural Killer (NK) cells." (PMID 39410010, 2024). "We provide evidence that Snhg15, a cancer-related lncRNA, recruits DNMT1 to the Ncam1 promoter through RNA/DNA triplex structure formation and the interaction with DNMT1." (PMID 37880732, 2023). "Cancer cell-derived fibroblast growth factor 2 (FGF2) can facilitate TAM survival and migration through AKT/ERK signaling, activated by neural cell adhesion molecule 1-enhanced classical FGF receptor 1 (FGFR1) and intracellular FGF2/FGFR1 signaling." (PMID 33995371, 2021). "Cancer cells secrete factors such as NGF, ARTN, CXCL12/SDF-1 which attract Schwann cells, and Schwann cells secrete GDNF, TGF-β and provide NCAM-1-mediated cell-cell interaction to promote cancer cell migration and aggressiveness." (PMID 33050151, 2020). "Seven of these predicted proteins (NCAM1, CNTN1, SCG2, CADM1, IL-8, NPTX1, and APOD) were identified in five databases (SignalP 4.1, SecretomeP 2.0, Vesiclepedia, Human Cancer Secretome, and Plasma Proteome), giving support to their relevance in NSCLC." (PMID 31455042, 2019). "Further, several genes at central nodes in the sub-network have cell-cell and cell-matrix adhesion functions and were described in numerous human cancer entities: CTNNA1, NCAM1, and GFRA1." (PMID 27172797, 2016). "The use of the CRISPR/Cas9 method to edit HLA-G from these cancer cells has indeed succeeded in reversing the induction mediated by HLA-G in wild-type RCC7 cells, demonstrating the direct implication of HLA-G in the regulation of NCAM1 expression." (PMID 39358558, 2024). "The described negative correlation of Ncam1 expression and cell motility in the context of cancer is in line with our findings." (PMID 37880732, 2023). "FAM159B did not co-localise with NCAM1, 5-HT, or somatostatin-14/28 in any of the cancer cell lines." (PMID 36362289, 2022). "It is hoped that these investigations will generate answers to critical questions that relate to the role of not just PrPC but also NCAM1 and the respective ZIP transporters in the context of cancer and neurodegenerative disease." (PMID 27879349, 2016).
infection (107 papers, 2004 to 2026). The state of being infected such as from the introduction of a foreign agent such as serum, vaccine, antigenic substance or organism. "Decreases in its NCAM-1/sCD56 concentration may be associated with two phenomena confirmed in the course of infection with SARS-CoV-2." (PMID 38673514, 2024). "LM90SB2 infection significantly upregulated the mRNA and protein expression levels of N-cadherin and NCAM1 in TGCs and enhanced TGC migration, while these effects were gradually attenuated with the sequential deletion of InlA, InlB and LLO." (PMID 42121802, 2026). "The significantly downregulated genes (NEAT1, TPM3, ZNHBA, CKLF, and OSBPL8) and the upregulated genes (ITMZC, IFNG, CD69, DNAJB9, and LYST) in NCAM1+FCGR3A+dNK cells after infection were also analyzed." (PMID 38730500, 2024). "Next, we analyzed the DEGs in the dNK subsets (NCAM1+FCGR3A−dNK and NCAM1+FCGR3A+dNK) after infection." (PMID 38730500, 2024). "To further demonstrate the requirement of NCAM1 for infection by ZIKV, we knocked out NCAM1 in U-251 MG cells using two different CRISPR/Cas9 sgRNAs." (PMID 32753727, 2020). "This included three receptor–RBP pairs for which mRNA levels were significantly associated with infection in the analyses (Cedar–EFNB1, Lujo–NRP2 and LCMV–DAG1), versus four with no apparent association (HCV–SCARB1, Cedar–EFNA2, SFTSV–MYH9 and rabies–NCAM1)." (PMID 39747691, 2025). "Similarly, lower expression of other immune subset genes (such as NK marker NCAM1) in blood in TB patients may also relate to migration of lymphocytes or natural killer cells from the peripheral blood to the site of infection." (PMID 31821366, 2019). "Further IFN and antiviral related proteins were upregulated upon infection with PeV-A3 (EIF2AK2, STAT1), or PeV-A1 (NCAM1, POM121), and downregulated upon PeV-A1 infection (EIF4G1, UBE2N, RANBP2, FLNA)." (PMID 38514653, 2024). "Then, to better understand the impairment of host polysialylation in T. cruzi infection, we investigated whether NCAM1 and SCN5A would be differentially modulated in hiPSC-CM and SH-SY5Y during infection." (PMID 39321148, 2024).
adenocarcinoma (52 papers, 2007 to 2025). A common cancer characterized by the presence of malignant glandular cells. "UMAP analysis of scRNA-seq separated PDX 224R into 3 adenocarcinoma clusters and 5 neuroendocrine clusters, which varied in AR and NCAM1 (CD56) expression, and enrichment of NE and AR signatures." (PMID 34413304, 2021). "Prostate biopsy revealed adenocarcinoma with Gleason score 4 + 5 accompanied by neuroendocrine differentiation, which was positive for PSA, synaptophysin, and NCAM1/CD56 by immunohistochemistry." (PMID 33413292, 2021). "We performed IHC to measure the expression of PROX1 along with NCAM1, AR, and the AR target, PSA, using tissue sections from samples collected at multiple time points (i.e., pre-castration adenocarcinoma [LTL331], 12 weeks post-castration, and relapsed NEPC [LTL331R])." (PMID 40454483, 2025). "Interestingly, NCAM1 is solely expressed in t-NEPC but not in CRPC-adenocarcinoma cells." (PMID 39183332, 2024).
psychiatric disorder (21 papers, 2011 to 2025). A disorder characterized by behavioral and/or psychological abnormalities, often accompanied by physical symptoms. "Among genes mapped to loci shared between AN and psychiatric disorders, several immune-related genes were implicated, including the C4A, C4B, NCAM1, HLA-B, HLA-C, and HLA-E genes." (PMID 37658054, 2023). "In conclusion, our data suggest the involvement of state- (i.e., HGF, S100B, and VEGF receptor 2) and trait (i.e., APP, GDNF, and NCAM-1) markers associated with neuroplasticity in the pathology of psychiatric disorders." (PMID 32439851, 2020). "Our results suggest that CSF APP, GDNF, and NCAM-1 levels are associated with psychiatric disorders, and that CSF HGF, S100B, and VEGF receptor 2 levels are related to psychiatric symptoms." (PMID 32439851, 2020). "Apparently, NCAM1 can be considered a general vulnerability factor for neurological and psychiatric disorders." (PMID 36199823, 2022). "Another strong candidate that emerged from the study was NCAM1, located in the NCAM1–TTC12–ANKK1–DRD2 gene cluster, which has been previously linked to smoking and alcohol use, but also to psychiatric disorders." (PMID 34944615, 2021). "Changes in levels of proteolytic product of NCAM1 and other adhesion molecules have been reported in cerebrospinal fluid and serum from patients with AD and psychiatric disorders." (PMID 33548223, 2021). "However, only two genes (i.e., HSP90B1 and NCAM1) show the same directional effects across all the 14 psychiatric disorders and the others display opposite directional effects on two or more disorders." (PMID 34895209, 2021). "Interestingly, NCAM1, ASTN2, and PDE4B are known to play important roles in regulating synaptic function and are implicated in human psychiatric disease." (PMID 26694817, 2015). "Overall, pleiotropic variants between gastrointestinal tract diseases and psychiatric disorders were extensively distributed, with several loci especially highlighted between certain trait pairs, such as 1q32.1 (INAVA), 19q13.33 (FUT2), 11q23.2 (NCAM1), and 1p32.3 (LRP8)." (PMID 36753304, 2023). "Finally, it cannot be determined whether the alteration of expression, processing or clearance of significant proteins (i.e., APP, GDNF, HGF, NCAM-1, S100B, and VEGF receptor 2) results in the association with psychiatric disorders." (PMID 32439851, 2020).
neurological disorders (12 papers, 2013 to 2025). "NCAM1 gene encodes a neural cell adhesion molecule critical for neuronal interactions and network formation, and its abnormal expression is linked to various neurological disorders." (PMID 40520613, 2025).
inflammatory myopathies (6 papers, 2013 to 2025). "Structural muscle genes (ACTA1, TTN) were reduced to levels similar to those in DM, while markers of muscle regeneration (NCAM1, PAX7, MYH3, MYH8) were only mildly increased compared to normal muscle, and lower than in other inflammatory myopathies." (PMID 41441888, 2025).
kidney diseases (6 papers, 2015 to 2023). "In this work, we discovered 20 top eccDNA hub genes in which NCAM1, NFATC1, PRKCB, LEF1, PRKAG2, and GRM8 were strongly linked to a variety of kidney disorders." (PMID 36967395, 2023). "Meanwhile, NCAM1+ cells, found in human fetal kidneys, retain their nephrogenic potential during in vitro culture and elicit beneficial effects on the progression of kidney disease." (PMID 34948246, 2021).
neurodegenerative disease (4 papers, 2015 to 2025). A disorder of the central nervous system characterized by gradual and progressive loss of neural tissue and neurologic function. "NCAM1 has previously been implicated in neurodegenerative diseases, and therefore was prioritized for quantification by ELISA in patient sera." (PMID 35148379, 2022).
peripheral nerve disease (1 paper, 2021). "In addition to NF-L, we evaluated NCAM-1, a novel blood biomarker with potential relevance to peripheral nerve disease." (PMID 33692503, 2021).
NCAM1 also shares sentences with these, for which no sentence is quoted: T-cell lymphoma (41 papers); neuroendocrine carcinoma (32); squamous cell carcinoma (28); multiple myeloma (26); endometriosis (25); rhabdomyosarcoma (24); carcinoids (21); hepatocellular carcinoma (20); hematological malignancies (18); Obesity (17); renal cell carcinoma (17); rheumatoid arthritis (17); Sepsis (17); HIV-1 infection (16); sarcoma (14); non-small cell lung carcinoma (13); Infertility (12); Autoimmunity (11); large cell neuroendocrine carcinoma (11); LGL leukemia (11); lymphopenia (11); papillary thyroid carcinoma (11); thyroid (11); lung adenocarcinoma (10); multiple sclerosis (10); sarcoidosis (10); thyroid cancer (10); Crohn disease (9); preeclampsia (9); synovial sarcoma (9).
A further 518 diseases each share a sentence with NCAM1 in 8 papers or fewer.